ALDH3A1 (aldehyde dehydrogenase 3 family member A1)
Diseases named in the same sentence as ALDH3A1 in open-access papers (continued):
Sharing a sentence is not in itself a finding about the gene and the disease.
Hyperglycemia (4 papers, 2020 to 2023). An increased concentration of glucose in the blood. "The results indicate that TGF-β shields RGCs from hyperglycemia-induced damage through the upregulation of ALDH3a1, along with other antioxidant and stress response proteins like HO-1, Nrf2, and HIF-1α." (PMID 37508004, 2023). "Summarizing the results, our findings demonstrated that TGF-β1 protected RGCs against hyperglycemia-induced oxidative damage by promoting cell antioxidation and neuroprotection pathways, including Nrf2/Keap1/ALDH3A1/HO-1 signaling." (PMID 32899874, 2020). "Additionally, ALDH3a1 has been investigated in relation to the neuroprotective mechanisms of TGF-β in preventing hyperglycemia-induced RGC death." (PMID 37508004, 2023). "In aldh3a1 knockout zebrafish mutants, increased 4-HNE concentrations disrupted the pancreas formation, which inhibited insulin expression and thereby facilitated hyperglycemia and a retinal vasodilatory phenotype." (PMID 35114580, 2022). "In zebrafish, knockout of the RCS detoxifying enzymes glyoxalase 1 (Glo 1), aldehyde dehydrogenase 3a1 (Aldh3a1) and aldo-ketoreductase 1a1a (Akr1a1a) showed a signature of elevated RCS which specifically regulated glucose metabolism, hyperglycemia and diabetic organ damage." (PMID 35114580, 2022).
leukemia (4 papers, 2018 to 2023). A malignant (clonal) hematologic disorder, involving hematopoietic stem cells and characterized by the presence of primitive or atypical myeloid or lymphoid cells in the bone marrow and the blood. "Moreover, studies have demonstrated that ALDH1A1 and ALDH3A1 are involved in the metabolism of ROS and reactive aldehydes in HSCs69,70, which may play important roles in HSC biology and leukaemia transformation." (PMID 36651035, 2023).
pterygium (4 papers, 2009 to 2022). A wedge-shaped fibrovascular lesion arising from the bulbar conjunctiva and extending to the cornea. "The previous study revealed Aldh3a1 was significantly upregulated in pterygium and further increased in recurrent pterygium patients." (PMID 36539822, 2022). "A previous study had found ALDH3A1 to be among the 25 most abundant transcripts in an un-normalized un-amplified pterygium cDNA library." (PMID 24825356, 2014). "Levels of ALDH3A1 in primary cultured pterygium and conjunctiva fibroblast cells and epithelial cells were analyzed by western blot." (PMID 24825356, 2014). "On immunofluorescent staining in pterygium and conjunctiva tissues (left and middle columns), ALDH3A1 was found to be present in both conjunctival and pterygium epithelium, with a stronger expression in pterygium than in conjunctiva." (PMID 24825356, 2014). "Results showed that ALDH3A1 was more highly expressed in pterygium fibroblast cells than conjunctiva fibroblast cells." (PMID 24825356, 2014). "The dysregulation of ALDH3A1 in pterygium tissue may be attributed to abnormal control of oxidative stress or proliferation." (PMID 24825356, 2014).
colon carcinoma (3 papers, 2014 to 2021). "Interestingly, in human patients affected with colon carcinoma, these genes (ALDH3A1, CLDN2 and CTEN) also have been associated with poor clinical outcomes." (PMID 24884630, 2014). "Consistent with preceding studies, we demonstrated that ALDH3A1 displayed a high expression level in metastasis colon cancer cells compared with primary colon cancer cells and provided potential biomarkers to develop new therapy to target stem cell caused metastasis." (PMID 34234849, 2021). "This speculation is supported by several pieces of evidence, demonstrating a specific elevated expression of ALDH1B1 in colon cancer; ALDH3B1 in lung, breast, ovarian, and colon cancer; ALDH3A1 in lung cancer; and ALDH7A1 in prostate cancer." (PMID 35582039, 2020). "Noticeably, the colon cancer stem cell marker, ALDH3A1, was markedly up regulated in R cells." (PMID 24884630, 2014).
diabetes (3 papers, 2016 to 2025). "Regarding diabetes and DR, studies utilizing an Aldh3a1 knockout zebrafish model have revealed the impaired detoxification of 4-HNE after Aldh3a1 knockout." (PMID 37508004, 2023).
glioblastoma (3 papers, 2018 to 2024). The most malignant astrocytic tumor (WHO grade IV). "Moreover, the upregulation of ALDH3A1 is implicated in the development of temozolomide-resistant glioblastoma cells, primarily due to impaired ferroptosis, further highlighting the role of ALDH3A1 in cancer resistance mechanisms." (PMID 39534872, 2024). "In addition to confirming recent findings that Wnt signaling promotes chemoresistance of glioblastoma cells, our data suggests that a possible mechanism of this association is the down regulation of ALDH3A1 expression in response to pathway inhibition." (PMID 29854309, 2018). "Previous studies reported that ALDH3A1 was involved in the Wnt/β-catenin signaling pathway mediated glioblastoma resistance to temozolomide." (PMID 35116021, 2021). "Taken together, our study suggests that previous observations concerning Wnt signaling blockade to reduce chemoresistance in glioblastoma is at least in part mediated by inhibition of ALDH3A1." (PMID 29854309, 2018). "To reveal effect of ALDH3A1 knock-down on glioblastoma stem-like cells, we tested the expression of several established stem cell genes in our genetically modified cell models." (PMID 29854309, 2018). "However, we provide evidence for ALDH3A1 inhibition to function as sensitizer to the glioblastoma standard of care chemotherapeutic agent." (PMID 29854309, 2018). "Our results suggest that ALDH3A1 in glioblastoma is a target gene of the canonical Wnt signaling and we provide functional evidence that pharmacological inhibition of the pathway by porcupine inhibition increases susceptibly to TMZ treatment at least in part due to down-regulation of ALDH3A1." (PMID 29854309, 2018). "Our findings also suggest that ALDH3A1 may be a promising therapeutic target for glioblastomas resistant to the standard of care treatment." (PMID 29854309, 2018). "Our data also indicate that ALDH3A1 may regulate TMZ sensitivity in glioblastoma cells independently of the MGMT promoter methylation status." (PMID 29854309, 2018).
head and neck cancer (3 papers, 2017 to 2022). A primary or metastatic malignant neoplasm affecting the head and neck. "This knowledge will help to guide our translational strategy of applying ALDH3A1 activators in the clinic to prevent radiation-related hyposalivation in head and neck cancer patients." (PMID 35707206, 2022).
liver cancer (3 papers, 2016 to 2022). An epithelial or non-epithelial malignant neoplasm that arises from the liver. "These evidences are consistent with our observation on the high expression of ALDH1A1 and ALDH3A1 in viral-infected liver cancer with poor prognosis." (PMID 32184801, 2020). "The results showed that ALDH1A1, ALDH1L1, ALDH1L2, ALDH3A1, ALDH3A2, ALDH5A1, and ALDH8A1 gene expressions were significantly different between liver cancer and normal tissues." (PMID 34928471, 2022).
anemia (2 papers, 2018 to 2025). A reduction in the number of red blood cells, the amount of hemoglobin, and/or the volume of packed red blood cells. "The presence of rare allele of polymorphism p.Pro329Ala (rs2228100) in component of cyclophosphamide metabolic pathway, aldehyde dehydrogenase ALDH3A1 gene, influenced the risk of recurrent anemia and leukopenia." (PMID 29507678, 2018). "The recurrence of anemia in four or more cycles of FAC chemotherapy was connected to the presence of the rare allele G of variant p.Pro329Ala in ALDH3A1 gene (rs2228100) and common homozygote CC of another ABC transporter gene polymorphism – ABCB1 p.Ile1145= (rs1045642)." (PMID 29507678, 2018). "Similarly, among patients with the GG genotype of the ALDH3A1 gene, the mean anemia grade showed a significant increase after the fourth cycle of the AC regimen compared to baseline (p < 0.05)." (PMID 40283974, 2025). "Qualitative hematological toxicity variables, including thrombocytopenia, leukopenia, neutropenia, lymphocytopenia, and anemia, were assessed at five different time points for their correlation with various alleles of the CYP2C19, ALDH3A1, SLC22A16, and ABCB1 genes." (PMID 40283974, 2025).
asthma (2 papers, 2012 to 2021). "ALDH3A1 was reported as a potential biomarker for precise diagnosis of difficult-to-control asthma." (PMID 34876009, 2021).
Astigmatism (2 papers, 2021 to 2023). A type of refraction error associated with abnormal curvatures on the anterior and/or posterior surface of the cornea. "The association of ALDH3A1 with intraocular pressure and refractive astigmatism have also been observed." (PMID 37990318, 2023).
diabetic retinopathy (2 papers, 2020 to 2021). "Considering that antioxidant signal transduction is a promising therapeutic target in retinopathy diseases, targeting TGF-β1 to promote Nrf2/Keap1/ALDH3A1/HO-1 signaling may be a candidate therapeutic approach for diabetic retinopathy." (PMID 32899874, 2020). "The expression of ALDH3A1 is suggested to play an important role in the stress response and the anti-oxidation pathway for the protection of RGCs, transforming growth factor-beta in the treatment of diabetic retinopathy and corneal cells against ultra-violet damage." (PMID 34445296, 2021).
esophageal cancer (2 papers, 2015 to 2019). A primary or metastatic malignant neoplasm involving the esophagus. "We also observed that ALDH2 is expressed at high level by almost all seven analyzed cancer types except for skin cancer, whereas the expressions of ALDH3A1 and ALDH3A2 are higher in lung, pancreatic, and esophagus cancer." (PMID 30220009, 2019).
lung diseases (2 papers, 2020 to 2021). "Although little is known about the association of ALDH isoforms with lung diseases, ALDH1a1 and ALDH3a1 have been reported to be expressed in the human airway epithelium." (PMID 34425896, 2021). "KEGG analysis suggested that metabolism of xenobiotics by cytochrome P450 (CYP1B1, CYP1A1 and ALDH3A1), an important signalling pathway that influences the xenobiotic metabolizing capability of the lung and the risk of developing of lung diseases, was associated with COPD." (PMID 32961012, 2020).
lymph node metastasis (2 papers, 2020 to 2025). "Lower ALDH3A1 expression in OSCC tissues was associated with a higher incidence of lymph node metastasis (LNM)." (PMID 32201532, 2020). "We found significant associations between the ALDH3A1 protein expression levels in OSCC and the histological grade, pT stage, and lymph node metastasis." (PMID 40657474, 2025). "Tumors with advanced pT stages and lymph node metastasis had a higher frequency of weak ALDH3A1 expression." (PMID 40657474, 2025). "In addition, we found that weak ALDH3A1 expression was correlated with lymph node metastasis (p < 0.001)." (PMID 40657474, 2025).
ovarian carcinoma (2 papers, 2019 to 2022). A malignant neoplasm originating from the surface ovarian epithelium. "ALDH1A2, ALDH1B1, and ALDH9A1 were downregulated in the ovarian cancer cells compared to the expression in HOSE cells, whereas ALDH3A1 was upregulated in the ovarian cancer cells." (PMID 31615043, 2019).
triple-negative breast carcinoma (2 papers, 2024 to 2025). An invasive breast carcinoma which is negative for expression of estrogen receptor (ER), progesterone receptor (PR), and human epidermal growth factor receptor 2 (HER2). "Another study also demonstrated that ALDH3A1-induced circadian rhythm could regulate the population of ALDH-positive triple-negative breast cancer cells." (PMID 38607733, 2024).
acute leukemia (1 paper, 2022). A clonal (malignant) hematopoietic disorder with an acute onset, affecting the bone marrow and the peripheral blood. "We also demonstrated that KMT2A-r acute leukemia patients overexpress three genes (ALDH3A1, PIK3R2, and TYMP) with interaction annotation to 5-Fluorouracil." (PMID 35734412, 2022).
acute lung injury (1 paper, 2026). A condition of lung damage that is characterized by bilateral pulmonary infiltrates (pulmonary edema) rich in neutrophils, and in the absence of clinical heart failure. "The in vivo results showed that oral IMP activated the AHR/ALDH3A1 and Nrf2/HO-1/GPX4 pathways in lung tissue, thus improving lung dysfunction and inflammation in acute lung injury (ALI) mice induced by LPS." (PMID 41513604, 2026).
alopecia (1 paper, 2025). Hair loss usually from the scalp. "Among patients carrying the GC+CC genotype of the ALDH3A1 gene, peripheral neuropathy severity significantly increased after cycle two, skin toxicity severity increased after cycle one, and alopecia severity increased after all chemotherapy cycles compared to baseline (p-value < 0.05)." (PMID 40283974, 2025).
behavioural disorders (1 paper, 2023). "There is evidence that ALDH1A1 and ALDH3A1 are important for transparency of the cornea, whereas OXTR has been linked to behavioural disorders and is known to regulate parturition." (PMID 37363400, 2023). "The connection between ALDH1A1 and ALDH3A1 loss and corneal opacities, and OXTR loss and prolonged labour and behavioural disorders provides a new explanation for the extracutaneous features of RXLI." (PMID 37363400, 2023).
cataract (1 paper, 2010). Partial or complete opacity of the crystalline lens of one or both eyes that decreases visual acuity and eventually results in blindness. "This is collaborated with recent data showing that Aldh3a1 knockout mice develop cataracts in the lens although ALDH3A1 protein expression is essentially confined to the cornea." (PMID 21203538, 2010).
endometrial cancer (1 paper, 2024). Primary or metastatic malignant neoplasm involving the endometrium (mucous membrane that lines the endometrial cavity). "The proteomic profiling of endometrial cancer cell lines revealed that ECC-1 and RL95-2 shared the ALDH isoforms ALDH3A1, ALDH3A2, ALDH3B1, ALDH3B2, ALDH7A1, ALDH9A1, and ALDH18A1 in their proteome." (PMID 38893151, 2024).
hearing loss (1 paper, 2022). "However, proteomic analysis showed a significant increase in protein expression of Tmem 33, Pgm1, Eif3f, Rps24, Cct8, Hsd17b4, Aldh3a1, Ddost, Aldh3a1, Eif3c, Luc7l2, and Acadvl—proteins with known roles in hearing loss." (PMID 36649043, 2022).
oral cancer (1 paper, 2020). "Furthermore, identifying dysregulated ALDH3A1 expression in OSCC cells will help us better understand tumor progression and metastasis, and suggest a possible therapeutic strategy for oral cancer." (PMID 32201532, 2020).
osteonecrosis (1 paper, 2024). A none disease characterized by death of bone tissue due to a lack of blood supply. "In this study, we identified 30 plasma proteins positively associated with osteonecrosis, and in particular, HEBP1 significantly increased the risk of osteonecrosis and ALDH3A1 suggestive increased the risk of osteonecrosis." (PMID 39119575, 2024). "Besides, we also found the positive association between Aldehyde dehydrogenase 3A1 (ALDH3A1) and osteonecrosis risk." (PMID 39119575, 2024). "Future studies further validate the association by examining whether anti-HEBP1/ALDH3A1 therapeutic antibodies have a role in osteonecrosis." (PMID 39119575, 2024). "Despite the lack of pharmacological information on HEBP1 and ALDH3A1, it remains a promising prognostic biomarker and therapeutic marker for osteonecrosis." (PMID 39119575, 2024).
osteosarcoma (1 paper, 2014). A usually aggressive malignant bone-forming mesenchymal neoplasm, predominantly affecting adolescents and young adults. "Therefore in canine osteosarcoma cells, ALDH3A1 expression may contribute to the resistance of the CSC pool to chemotherapeutic drugs." (PMID 24416158, 2014).
pancreatic adenocarcinoma (1 paper, 2025). "Next, the expression of ALDH1L1, ALDH3A1, ALDH3B1, and ALDH5A1 in pancreatic adenocarcinoma (PAAD) samples was compared with that of matching TCGA and GTEx normal samples using GEPIA2." (PMID 40868269, 2025).
pulmonary arterial hypertension (1 paper, 2024). Pulmonary arterial hypertension (PAH) is a group of diseases characterized by mean pulmonary artery pressure >20 mmHg and elevated pulmonary arterial resistance leading to right heart failure. "The glycolysis genes (ACSS2, ALAS2, ALDH3A1, ADOC3, NT5E, and TALDO1) identified in this study play important roles in the development of pulmonary arterial hypertension, providing new evidence for the involvement of glycolysis in PAH." (PMID 38837574, 2024).
skin melanoma (1 paper, 2019). "Similarly, in skin melanoma samples, normal keratinocytes showed a faint cytoplasmic ALDH3A1 expression." (PMID 31817719, 2019).
soft tissue sarcoma (1 paper, 2020). A malignant neoplasm arising from muscle tissue, adipose tissue, blood vessels, fibrous tissue, or other supportive tissues excluding the bones. "This is in agreement with our survival analysis on soft-tissue sarcomas demonstrating that upregulated expression of ALDH6A1 but not ALDH1A1 or ALDH3A1 significantly correlates with poor survival when combined with other genes identified in our model, i.e., CDH15, MYOD1, SOX4, ARMCX1, and RYK." (PMID 31941033, 2020).
Squamous Cell Carcinoma in situ (1 paper, 2024). "Interestingly, neither Squamous Cell Carcinoma in situ (SCCIS) nor cSCC showed a significant upregulation of ALDH3A1 and IGFBP2, and ALDH3A1 was even found to be downregulated in cSCC." (PMID 38566927, 2024).
Thrombocytopenia (1 paper, 2025). A reduction in the number of circulating thrombocytes. "Patients carrying the GC+CC genotype of the ALDH3A1 gene also demonstrated a significant increase in thrombocytopenia grades after the first, second, and third cycles of the AC regimen (p-value < 0.05)." (PMID 40283974, 2025).
uremia (1 paper, 2019). A clinical syndrome associated with the retention of renal waste products or uremic toxins in the blood. "Therefore, decreased levels of ALDH3A1 could be a further important factor in uremic pathophysiology, both with respect to the increased oxidative stress in uremia and to impaired protein function." (PMID 31385015, 2019).